RPS27A (ribosomal protein S27a)
Description:
[Ubiquitin]: Exists either covalently attached to another protein, or free (unanchored). When covalently bound, it is conjugated to target proteins via an isopeptide bond either as a monomer (monoubiquitin), a polymer linked via different Lys residues of the ubiquitin (polyubiquitin chains) or a linear polymer linked via the initiator Met of the ubiquitin (linear polyubiquitin chains). Polyubiquitin chains, when attached to a target protein, have different functions depending on the Lys residue of the ubiquitin that is linked: Lys-6-linked may be involved in DNA repair; Lys-11-linked is involved in ERAD (endoplasmic reticulum-associated degradation) and in cell-cycle regulation; Lys-29-linked is involved in proteotoxic stress response and cell cycle; Lys-33-linked is involved in kinase modification; Lys-48-linked is involved in protein degradation via the proteasome; Lys-63-linked is involved in endocytosis, DNA-damage responses as well as in signaling processes leading to activation of the transcription factor NF-kappa-B. Linear polymer chains formed via attachment by the initiator Met lead to cell signaling. Ubiquitin is usually conjugated to Lys residues of target proteins, however, in rare cases, conjugation to Cys or Ser residues has been observed. When polyubiquitin is free (unanchored-polyubiquitin), it also has distinct roles, such as in activation of protein kinases, and in signaling. [Small ribosomal subunit protein eS31]: Component of the 40S subunit of the ribosome. Part of the small subunit (SSU) processome, first precursor of the small eukaryotic ribosomal subunit. During the assembly of the SSU processome in the nucleolus, many ribosome biogenesis factors, an RNA chaperone and ribosomal proteins associate with the nascent pre-rRNA and work in concert to generate RNA folding, modifications, rearrangements and cleavage as well as targeted degradation of pre-ribosomal RNA by the RNA exosome.
Synonyms: UBA80; UBCEP1; UBCEP80; S27A; eS31; CEP80; HEL112
Tractability: Small molecule: an approved drug acts on it; a structure with a bound ligand is known; a high-quality ligand is known. Antibody: its Gene Ontology location is reachable by antibodies, with high confidence. PROTAC: UniProt records ubiquitination sites on it; ubiquitination databases record sites on it; its protein half-life has been measured; a small molecule that binds it is known. Other modalities: a drug acting on it is in phase 2 or 3 trials.
Target class: Other cytosolic protein
Gene: Protein-coding gene on chromosome 2 (55,229,447 to 55,236,044, forward strand). Ensembl gene ENSG00000143947.
Subcellular location: Cytoplasm (Small ribosomal subunit protein eS31); Nucleus, nucleolus; Cytoplasm (Ubiquitin); Nucleus
Subcellular location (Human Protein Atlas): Cytosol; Endoplasmic reticulum; Nucleoli; Acrosome; Equatorial segment
Pathways (Reactome):
Immune System: AMPK-induced ERAD and lysosome mediated degradation of PD-L1(CD274); Activation of IRF3, IRF7 mediated by TBK1, IKKε (IKBKE); Activation of NF-kappaB in B cells; Alpha-protein kinase 1 signaling pathway; Antigen processing: Ubiquitination & Proteasome degradation; CLEC7A (Dectin-1) signaling; DDX58/IFIH1-mediated induction of interferon-alpha/beta; Dectin-1 mediated noncanonical NF-kB signaling; Downstream TCR signaling; ER-Phagosome pathway; FCERI mediated NF-kB activation; GSK3B-mediated proteasomal degradation of PD-L1(CD274); IKK complex recruitment mediated by RIP1; IRAK1 recruits IKK complex; IRAK1 recruits IKK complex upon TLR7/8 or 9 stimulation; IRAK2 mediated activation of TAK1 complex; IRAK2 mediated activation of TAK1 complex upon TLR7/8 or 9 stimulation; ISG15 antiviral mechanism; Inactivation of CSF3 (G-CSF) signaling; Interferon alpha/beta signaling; Interleukin-1 signaling; JNK (c-Jun kinases) phosphorylation and activation mediated by activated human TAK1; MAP3K8 (TPL2)-dependent MAPK1/3 activation; NIK-->noncanonical NF-kB signaling; NOD1/2 Signaling Pathway; Negative regulation of FLT3; Negative regulators of DDX58/IFIH1 signaling; PD-L1(CD274) glycosylation and translocation to plasma membrane; Regulation of NF-kappa B signaling; Regulation of TBK1, IKKε (IKBKE)-mediated activation of IRF3, IRF7; Regulation of TBK1, IKKε-mediated activation of IRF3, IRF7 upon TLR3 ligation; Regulation of innate immune responses to cytosolic DNA; Regulation of signaling by CBL; SPOP-mediated proteasomal degradation of PD-L1(CD274); Signaling by CSF1 (M-CSF) in myeloid cells; TAK1-dependent IKK and NF-kappa-B activation; TICAM1, RIP1-mediated IKK complex recruitment; TICAM1,TRAF6-dependent induction of TAK1 complex; TICAM1-dependent activation of IRF3/IRF7; TNFR2 non-canonical NF-kB pathway
and 178 more pathways
Gene Ontology:
Molecular function: protein binding; RNA binding; structural constituent of ribosome; protein tag activity
Biological process: cytoplasmic translation; modification-dependent protein catabolic process; protein ubiquitination; translation
Cellular component: cytoplasm; cytosol; cytosolic ribosome; endoplasmic reticulum; extracellular exosome; extracellular region; membrane; nucleolus; nucleus; small-subunit processome; vesicle; cytosolic small ribosomal subunit; endocytic vesicle membrane; endoplasmic reticulum membrane; endosome membrane; mitochondrial outer membrane; nucleoplasm; plasma membrane; ribosome; synapse
Genetic constraint (gnomAD): Loss-of-function variants: 1 observed, 12.58 expected, observed/expected ratio (o/e) 0.0795, 90% interval 0.027 to 0.38. The upper end of that interval is the gene's LOEUF score, 0.38, which puts it in group 1 of 6, group 1 being the genes least tolerant of losing a copy. Missense variants: 80 observed, 150 expected, observed/expected ratio (o/e) 0.53, 90% interval 0.44 to 0.64. Synonymous variants: 58 observed, 51.45 expected, observed/expected ratio (o/e) 1.13, 90% interval 0.91 to 1.4.
Homologues: Orthologues: chimpanzee RPS27A (100% identical), dog RPS27A (100% identical), guinea pig RPS27A (100% identical), macaque RPS27A (100% identical), pig RPS27A (100% identical), tropical clawed frog rps27a (100% identical), mouse Rps27a (99% identical), rat Rps27a (99% identical), rat Rps27a-ps2 (93% identical). Paralogues in human: UBA52 (56% identical), UBC (56% identical), ZFAND4 (35% identical), ANKUB1 (31% identical), NEDD8 (28% identical), UBD (24% identical), UBL4A (20% identical), ISG15 (18% identical), UBL4B (18% identical), UBB (8% identical).
Diseases named in the same sentence as RPS27A in open-access papers:
RPS27A is named in the same sentence as 48 diseases in open-access papers, as found by Europe PMC text mining. Sharing a sentence is not in itself a finding about the gene and the disease. The quoted sentences say what the papers report.
leukemia (9 papers, 2016 to 2025). A malignant (clonal) hematologic disorder, involving hematopoietic stem cells and characterized by the presence of primitive or atypical myeloid or lymphoid cells in the bone marrow and the blood. "In contrast, RPS27A encodes a ribosomal protein that has been implicated in the promotion of proliferation and inhibition of apoptosis, and is upregulated in leukemia and colorectal cancer." (PMID 27608846, 2016). "RPS27A has been shown to exert a regulatory effect on cell cycle progression, promote proliferation, and have an inhibition effect on apoptosis of leukemia cells." (PMID 38694515, 2024). "RPS27A has also been reported to promote proliferation, regulate cell cycle progression, inhibit apoptosis and enhance chemoresistance in leukemia cells." (PMID 37888706, 2023). "The RPS27A was reported to regulate proliferation, promote cell progression and inhibit apoptosis of leukemia cells." (PMID 36354791, 2022). "RPS27A performs multifunction in ribosome biogenesis and protein PTMs, contributing to progression of leukemia or solid tumors." (PMID 34350460, 2021). "RPS27A can promote cell proliferation, regulate cell cycle progression, and inhibit the apoptosis of leukemia cells." (PMID 34150879, 2021). "RPS27a can promote proliferation, regulate cell cycle progression and inhibit apoptosis of leukemia cells." (PMID 26942564, 2016). "RPS27A and UBA52, which are hub proteins unique to papillary urothelial carcinoma in network A, have been found to be overexpressed in colon cancer, prostate cancer, and leukemia." (PMID 41342186, 2025).
breast carcinoma (5 papers, 2020 to 2024). "Recent studies have shown that RPS27A protein is abnormally expressed in colon cancer, kidney cancer, breast cancer and LUAD, and is associated with tumorigenesis." (PMID 39667820, 2024). "RPS27A is overexpressed in breast cancer, enhanceing EBV-encoded LMP1-mediated proliferation and invasion through stabilization of LMP1." (PMID 38418940, 2024). "RPS27A was overexpressed in actively proliferating cells, including chronic myeloid leukemia 34, colon 35, renal 36, and breast cancers." (PMID 32802186, 2020). "RPS27a is overexpressed in chronic myeloid leukemia; colon, renal, breast cancers and LUAD." (PMID 35073964, 2022). "One RP, ribosomal protein S27a (RPS27A), actively promotes proliferation in breast cancer, renal cancer, colon cancer, and chronic myeloid leukemia." (PMID 37701139, 2023).
chronic myeloid leukemia (5 papers, 2020 to 2025). "RPS27A is linked to colorectal cancer, hepatocellular carcinoma, chronic granulocytic leukemia, and renal cancer, with poor prognostic implications." (PMID 39796173, 2025).
hepatocellular carcinoma (5 papers, 2021 to 2025). A malignant tumor that arises from hepatocytes. "RPS27a is overexpressed in renal, breast and colon carcinomas, and its gene expression has been found to be markedly elevated in an oncomouse model of hepatocellular carcinoma." (PMID 35073964, 2022). "UBA52 and RPS27A genes were found to be differently over-expressed during hepatoma cell apoptosis." (PMID 34445327, 2021).
ovarian carcinoma (5 papers, 2021 to 2024). A malignant neoplasm originating from the surface ovarian epithelium. "Four of these factors (FGF18, HERC5, hsa-miR-202, and RPS27A) were found to be associated with ovarian cancer in previous literatures." (PMID 37609286, 2023). "The study identified genes with survival-related alternative splicing events in ovarian cancer, and RPS27A was one of the hub genes in the gene interaction network." (PMID 37609286, 2023). "In this paper, we identified the potential gene with prognosis-related AS event in ovarian carcinomas (the multiple genes presented in the network), and EIF3M, RPS27A, SNRNP200 and UBR4 were found at the core of gene interaction network." (PMID 34001978, 2021). "Secondly, we identified more accurate and reliable hub genes including EIF3M, RPS27A, SNRNP200 and UBR4, and we also performed an enrichment analysis to characterize the role of AS in ovarian cancer." (PMID 34001978, 2021).
renal carcinoma (5 papers, 2021 to 2025). A carcinoma arising from the epithelium of the renal parenchyma or the renal pelvis. "Previous studies have indicated that RPS27A was up-regulated in several cancers, including colorectal and renal cancers." (PMID 34257566, 2021). "A ubiquitin-fused RPS27A protein (Uba80) was reported related to apoptotic cell death and overexpressed in colon and renal cancer." (PMID 34350460, 2021). "In the case of renal cancer, GYS1 interacts with RPS27A and forms a complex of GYS1/RPS27A that can increase the nuclear transfer of p65." (PMID 39014491, 2024).
Alzheimer disease (3 papers, 2018 to 2024). A progressive, neurodegenerative disease characterized by loss of function and death of nerve cells in several areas of the brain leading to loss of cognitive function such as memory and language. "It was discovered that the levels of two of the four ribosomal fusion proteins encoded by human ubiquitins, RPS27A and UBA52, were elevated in patients with Alzheimer's disease and COVID-19 with Alzheimer's disease, respectively." (PMID 37521843, 2022).
lung adenocarcinoma (3 papers, 2022 to 2023). A carcinoma that arises from the lung and is characterized by the presence of malignant glandular epithelial cells.
lung carcinoma (3 papers, 2021 to 2025). "RPS27A (ribosomal protein), which plays an essential role in mRNA translation and ribosome assembly for the differentiation of cancer cells, was detected from the EVs of lung cancer cells associated with cancer cell migration and invasion." (PMID 35478925, 2021).
Cerebral ischemia (2 papers, 2024 to 2025). Restriction of arterial blood supply to the brain associated with insufficient oxygenation to support the metabolic requirements of the tissue. "Another study found that RPS27A drives neuroinflammation in cerebral ischemia–reperfusion injury via the NF-κB signaling pathway." (PMID 41020849, 2025). "Moreover, studying how RPS27A specifically affects the activation of microglial cells and the inflammatory response in the context of cerebral ischemia/reperfusion injury will be a focus of our subsequent research." (PMID 39039432, 2024).
cervical cancer (2 papers, 2021). A primary or metastatic malignant neoplasm involving the cervix. "Ribosomal protein S27A (RPS27A), the only key gene screened in this study associated with prognostic survival in cervical cancer patients, belongs to the ribosomal protein S27AE family." (PMID 34796111, 2021). "By observing the difference in the expression levels of key genes in the different types of cervical cancer and normal tissues, we found that most genes, such as RPS27A, RPS3, and EEF1B2, were significantly expressed in cervical cancer." (PMID 34796111, 2021).
clear cell renal carcinoma (2 papers, 2024 to 2025). A malignant epithelial neoplasm of the kidney characterized by the presence of lipid-containing clear cells within a vascular network. "In clear cell renal carcinoma, elevated expression of RPS27A has been linked to the activation of the NF-κB signaling pathway." (PMID 40409241, 2025). "Interestingly, previous studies have found that RPS27A mediates the interaction between GYS1 and NF-κB, promoting the phosphorylation and nuclear entry of p65 in clear cell renal cell carcinoma." (PMID 39039432, 2024).
glioma (2 papers, 2021 to 2025). A benign or malignant brain and spinal cord tumor that arises from glial cells (astrocytes, oligodendrocytes, ependymal cells). "In gliomas, elevated RPS27A expression has been associated with more aggressive gliomas." (PMID 40428295, 2025).
viral infection (2 papers, 2015 to 2021). "Other links to viral infection for these newly identified STING partners include the hepatitis B virus HBx protein that alters the intracellular distribution of RPS27a." (PMID 34541469, 2021).
acute leukemia (1 paper, 2022). A clonal (malignant) hematopoietic disorder with an acute onset, affecting the bone marrow and the peripheral blood. "RPS27A was also shown to be elevated in chronic myeloid leukemia (CML) and acute leukemia, and knockdown of RPS27A in CML K562 cell lines decreased cell proliferation, arrested cells at the S and G2/M phases, and promoted apoptosis." (PMID 34914197, 2022).
African trypanosomiasis (1 paper, 2022). "Topology analysis of the miRNA-gene network revealed three genes (RPS27A, UBA52 and GAPDH) involved in the regulation of critical pathways related to the development of African trypanosomiasis." (PMID 36354791, 2022).
asthenozoospermia (1 paper, 2023). "The expression of RPS27A is downregulated in patients with asthenozoospermia and patients exposed to oxidative stress (reactive oxygen species), indicating that it may be a protein marker for detecting spermatozoon motility." (PMID 38203385, 2023).
influenza (1 paper, 2025). An acute viral infection of the respiratory tract, occurring in isolated cases, in epidemics, or in pandemics; it is caused by serologically different strains of viruses (influenzaviruses) designated A, B, and C, has a 3-day incubation period, and usually lasts for 3 to 10 days. "The analysis revealed that the core targets of Chicoric acid against influenza are UBA52, UBC, HCK, CDKN1B, and RPS27A." (PMID 41303371, 2025).
ischemia (1 paper, 2025). A hypoperfusion of the BLOOD through an organ or tissue caused by a PATHOLOGIC CONSTRICTION or obstruction of its BLOOD VESSELS, or an absence of BLOOD CIRCULATION. "The potential role of RPS27A in myocardial Ischemia-Reperfusion (I/R) injury through mediating immune cell infiltration remains uncertain, as direct studies on this topic are lacking." (PMID 40409241, 2025). "Research suggests that RPS27A promotes the expression of inflammatory factors in microglial cells by regulating the PSMD12/NF-κB signaling axis, which facilitates immune cell infiltration into brain tissue and exacerbates brain damage in ischemia/reperfusion models." (PMID 40409241, 2025).
liver cancer (1 paper, 2016). An epithelial or non-epithelial malignant neoplasm that arises from the liver. "RPS27a are overexpressed in mouse liver cancer and some human tumors." (PMID 26942564, 2016).
non-small cell lung carcinoma (1 paper, 2022). A group of at least three distinct histological types of lung cancer, including non-small cell squamous cell carcinoma, adenocarcinoma, and large cell carcinoma. "The expression of RPS27a in A549 and H460 cells was higher than that in BEAS-2B cells and was highest in A549 cells, thus, indicating that the overexpression of RPS27a was associated with the progression of non-small cell lung cancer." (PMID 35073964, 2022).
osteoporosis (1 paper, 2025). A condition of reduced bone mass, with decreased cortical thickness and a decrease in the number and size of the trabeculae of cancellous bone (but normal chemical composition), resulting in increased fracture incidence. "Therefore, we speculate that as a ribosomal protein and ubiquitin precursor, RPS27A may participate in the pathogenesis of osteoporosis by influencing macrophage polarization through releasing certain signals." (PMID 41459514, 2025).
psoriasis (1 paper, 2024). An autoimmune condition characterized by red, well-delineated plaques with silvery scales that are usually on the extensor surfaces and scalp. "Additionally, in 18 psoriasis patients with a good response to methotrexate treatment, upregulated RPS27A protein participated in the activation of NF-κB." (PMID 39039432, 2024).
type 2 diabetes mellitus (1 paper, 2021). A type of diabetes mellitus that is characterized by insulin resistance or desensitization and increased blood glucose levels. "Researchers have shown that RPS27A may be a potential target of mesenchymal stem cells in treating type 2 diabetes mellitus (T2DM)." (PMID 34326892, 2021).